TTC6 (tetratricopeptide repeat domain 6)
Synonyms: C14orf25; NCRNA00291
Tractability: No criterion of Open Targets' tractability assessment is met for any kind of drug.
Gene: Protein-coding gene on chromosome 14 (37,595,629 to 38,041,442, forward strand). Ensembl gene ENSG00000139865.
Subcellular location (Human Protein Atlas): Centrosome; Basal body
Genetic constraint (gnomAD): Loss-of-function variants: 125 observed, 153.44 expected, observed/expected ratio (o/e) 0.81, 90% interval 0.7 to 0.94. The upper end of that interval is the gene's LOEUF score, 0.94, which puts it in group 4 of 6, group 1 being the genes least tolerant of losing a copy. Missense variants: 2,017 observed, 1,945.5 expected, observed/expected ratio (o/e) 1.04, 90% interval 1 to 1.08. Synonymous variants: 690 observed, 710.43 expected, observed/expected ratio (o/e) 0.97, 90% interval 0.91 to 1.03.
Homologues: Orthologues: chimpanzee TTC6 (98% identical), pig TTC6 (73% identical), dog TTC6 (72% identical), rabbit TTC6 (70% identical), rat Ttc6 (61% identical), mouse Ttc6 (60% identical), tropical clawed frog ttc6 (36% identical), zebrafish ttc6 (29% identical), macaque TTC6 (26% identical). Paralogues in human: CFAP70 (8% identical), TTC34 (7% identical), OGT (7% identical), TTC13 (6% identical), TTC7B (6% identical), TTC7A (6% identical), TTC8 (5% identical), TMTC1 (5% identical), TMTC3 (5% identical), IFT88 (5% identical), TMTC2 (5% identical), TMTC4 (4% identical), and 2 more.
Diseases named in the same sentence as TTC6 in open-access papers:
TTC6 is named in the same sentence as 5 diseases in open-access papers, as found by Europe PMC text mining. Sharing a sentence is not in itself a finding about the gene and the disease. The quoted sentences say what the papers report.
breast carcinoma (2 papers, 2020 to 2025). "The most frequently occurring fusion genes in each subtype were TTC6::MIPOL1 in HR+/HER2‒ breast cancers, LHFPL5::CLPSL1 in triple-negative breast cancer (TNBC), and TPTE2::MRPS31P2 in HER2+ breast cancers." (PMID 41213951, 2025). "The tetratricopeptide repeat domain 6, TTC6, has been shown to play a role in breast cancer, and in prostate cancer, there is evidence for a TTC6-MIPOL1 fusion." (PMID 32513296, 2020).
ciliopathies (1 paper, 2023). "Tetratricopeptide repeat protein 6 (TTC6) is another member of the tetratricopeptide repeat protein family and is considered a candidate gene for ciliopathies according to recent research into the morbid genome of ciliopathies." (PMID 37626901, 2023). "Within the context of the tetratricopeptide repeat protein family, TTC6 emerges as a significant member and has been identified as a plausible candidate gene for ciliopathies, stemming from contemporary investigations into the pathological genome of such conditions." (PMID 37626901, 2023).
TTC6 also shares sentences with these, for which no sentence is quoted: prostate carcinoma (2 papers); preeclampsia (1); triple-negative breast carcinoma (1).